LCN2 (lipocalin 2)
Diseases named in the same sentence as LCN2 in open-access papers (continued):
Sharing a sentence is not in itself a finding about the gene and the disease.
iron deficiency (10 papers, 2014 to 2025). "Specifically, stem cell senescence is observed to promote tumor initiation through the Nupr1–lipocalin-2 pathway via the induction of functional iron deficiency." (PMID 40977764, 2025). "In our current study, we found that LCN2 deficiency ameliorated serum iron deficiency and reduced aortic tissue ferroptosis in the CKD-VC mouse model." (PMID 39613734, 2024). "In line with our observations, a positive association was observed between upregulated LCN2 expression and iron deficiency anaemia in HD patients." (PMID 39613734, 2024). "To determine if Salmonella coinfection induces iron deficiency, we analyzed gastric expression of lipocalin-2, hepcidin, and fur, which are known to be regulated by iron and therefore serve as a functional readout of iron deficiency." (PMID 33443133, 2020). "Other direct stimulators of FGF-23 include Lipocalin 2 (LCN2, a marker of inflammation and an iron transporter), reduced oxygenation, iron deficiency, and Epo." (PMID 39684548, 2024). "Lcn2 deletion specifically prevented FGF23 elevations in response to inflammation, but not iron deficiency or phosphate, and administration of LCN2 increased serum FGF23 in healthy and CKD mice by stimulating Fgf23 transcription via activation of cAMP-mediated signaling in bone cells." (PMID 34334787, 2021).
renal carcinoma (10 papers, 2013 to 2025). A carcinoma arising from the epithelium of the renal parenchyma or the renal pelvis. "Iron-loaded Lcn-2 contributed to pro-tumor functions, whereas iron-free Lcn-2 had adverse effects in renal cancer." (PMID 33808732, 2021). "Since lipocalin-2 (LCN-2) represents an already-established biomarker for acute and chronic kidney pathologies, we aimed at elucidating its role in renal cancer." (PMID 31772326, 2020). "In order to verify the role of LCN-2 in renal cancer, we first analysed the survival probability of ccRCC patients by applying the R2 Genomics Analysis and Visualization Platform using the cancer genome atlas (TCGA) data, including 533 patients of the KIRC data set." (PMID 31772326, 2020). "In renal cancer, inhibiting PRMT1 resulted in decreased deposition of H3R4me2a at the Lcn2 promoter, attenuating the transcription of Lcn2 and resulting in a decrease in its expression." (PMID 38326807, 2024). "We provide evidence that iron-loaded Lcn-2 not only induces the ROS-Nfr2 axis, but also fosters ISR-dependent expression of SLC7A11 to attenuate erastin-induced ferroptosis in renal cancer." (PMID 34069743, 2021). "To determine LCN-2R expression, which is relevant for the uptake of LCN-2, we analysed LCN-2R mRNA and protein expression in whole-tissue homogenates from renal cancer samples compared with matched healthy adjacent control tissue." (PMID 31772326, 2020).
retinal degeneration (10 papers, 2019 to 2025). Degeneration of the retina. "In addition, LCN-2−/− neutrophils, as well as LCN-2−/− neutrophils treated with IFNλ, showed no degenerative changes, suggesting a pathogenic role of LCN-2 in retinal degeneration." (PMID 31552301, 2019). "Third, other modes of cell death, such as apoptosis and necrosis, have been identified as major contributors to retinal degeneration and their relationship to LCN2-induced ferroptosis should be investigated in further studies." (PMID 40375133, 2025). "In the light-induced retinal degeneration model, the neural retinal expression of LCN2 protein increased in a time-dependent manner, with significant increases at 3 and 7 days after light exposure." (PMID 40375133, 2025). "Our results demonstrate that LCN2 induced ferroptosis in light-induced retinal degeneration by increasing the Fe2+ level and promoting the activation of JNK, and subsequent inhibition of the SLC7A11-GSH-GPX4 axis." (PMID 40375133, 2025). "LCN-2 is involved in the acute stress response, with multiple innate immune functions in a retinal degeneration model." (PMID 35265399, 2022). "In the present study, we investigated the involvement of Lcn2 in retinal degeneration induced by elevated hydrostatic pressure using our two-chamber culture system." (PMID 34136483, 2021). "In agreement with our IF data, in mouse models of retinal degeneration, Müller cells were observed to respond to photoreceptor damage by expression of lcn2." (PMID 32183784, 2020). "Neutrophil gelatinase-associated lipocalin (NGAL, also known as lipocalin-2, LCN2), an important innate immune mediator, is known to be critically involved in sterile inflammation-mediated organ failure, fibrosis, cancer progression and retinal degeneration." (PMID 33292361, 2020). "However, other studies have shown that LCN2 is also involved in retinal pro-survival and anti-oxidative responses and can suppress inflammation and reduce retinal degeneration." (PMID 33292361, 2020). "Therefore, our NOD-SCID mouse data provides novel evidence that IFNλ triggers LCN-2 activation in neutrophils, thereby inducing transmigration into the retina and potentiating retinal degeneration." (PMID 31552301, 2019). "However, whether LCN2 regulates JNK activity in retinal degeneration, and the mechanistic link between JNK activation and light-induced photoreceptor ferroptosis, remain unresolved." (PMID 40375133, 2025). "Our findings suggest that LCN2 may be a potential therapeutic target for retinal degeneration." (PMID 40375133, 2025). "Therefore, LCN2 presents a new target for the treatment of retinal degeneration." (PMID 40375133, 2025). "Modulating Lcn2 and iron levels may be a promising therapeutic approach for retinal degeneration." (PMID 34136483, 2021). "However, WT neutrophils or LCN-2−/− neutrophils that have lower levels of extracellular integrin β1, even after IFNλ treatment, failed to cause such an effect, strongly suggesting that abnormal levels of LCN-2 released from the infiltrating neutrophils trigger retinal degeneration." (PMID 31552301, 2019). "However, another lipocalin family member (lipocalin-2, LCN2) may modulate inflammation in retinal degeneration by promoting cell survival responses and regulating the production of inflammatory proteins." (PMID 31367973, 2019). "However, the effects of LCN2 on ferroptosis in retinal degeneration remain unclear." (PMID 40375133, 2025). "Overall, these data suggest that deferoxamine treatment attenuated pressure-induced retinal degeneration by inhibiting endogenous increase of Lcn2, but not by inhibiting retinal uptake of extracellular Lcn2." (PMID 34136483, 2021). "However, the role of LCN2 in ferroptosis in photoreceptor cells in light-induced retinal degeneration has not been explored." (PMID 40375133, 2025).
autoimmune disease (9 papers, 2010 to 2024). A disorder resulting from loss of function or tissue destruction of an organ or multiple organs, arising from humoral or cellular immune responses of the individual to their own tissue constituents. "The toxic targets of LGT were mainly distributed in the downstream of the pathways, such as LCN2, IL6, IL1B, and CSF3, and ultimately target the inflammatory host defense autoimmunity, proinflammatory activities and other inflammatory reactions and autoimmune diseases." (PMID 36339610, 2022).
bacterial meningitis (9 papers, 2014 to 2025). Inflammation of the membranes surrounding the brain and spinal cord due to a bacterial infection. "Specifically, for lipocalin-2, this serves as a potential biomarker derived from cerebral spinal fluid for bacterial meningitis and a differentiating component between bacterial and fungal meningitis." (PMID 41061967, 2025). "In the discovery cohort, we identified lipocalin 2 (LCN2) as a potential biomarker of bacterial meningitis (BM) other than tuberculous meningitis." (PMID 32659386, 2020). "As a biological marker of acute bacterial meningitis, the detection of lipocalin 2 in CSF has a sensitivity of 81%, a specificity of 93%, a positive predictive value of 96% and a negative predictive value of 71%." (PMID 24885531, 2014). "CSF from group 1 (acute bacterial meningitis) showed higher levels of LCN2 than group 2 (acute viral meningitis)." (PMID 24885531, 2014). "All these data taken together, strongly suggest that lipocalin 2 can be used as a marker to help confirming acute bacterial meningitis." (PMID 24885531, 2014). "We next aimed to test whether lipocalin 2 can be detected in CSF from patients with acute bacterial meningitis." (PMID 24885531, 2014). "We aimed to investigate whether the detection of lipocalin 2, a protein of the acute innate immunity response, may be used as a marker for acute bacterial meningitis." (PMID 24885531, 2014). "We aimed to explore the detection of LCN2 in CSF as a marker of acute bacterial meningitis." (PMID 24885531, 2014).
cerebral infarction (9 papers, 2015 to 2024). An ischemic condition of the brain, producing a persistent focal neurological deficit in the area of distribution of the cerebral arteries. "In Spearman correlation analysis, serum LCN2 was not significantly correlated with NIHSS score (P > 0.05), while serum LCN2 was positively correlated with cerebral infarction volume (r = 0.161, P = 0.002)." (PMID 37543589, 2023). "Our data showed a positive correlation between serum LCN2 and cerebral infarct volume (r = 0.161, P = 0.002)." (PMID 37543589, 2023). "Improvement in neurological outcome after LCN2 mAb treatment was reflected in cerebral infarction and edema." (PMID 32872405, 2020). "Cerebral infarction, neurological deficits, infiltration of neutrophils, and BBB permeability were diminished in LCN2 deficient mice after tMCAo." (PMID 32872405, 2020). "In mice experiment, LCN2 increased gradually and peaked at 23 h after cerebral infarction mainly in astrocytes and endothelial cells." (PMID 31426811, 2019). "LCN2 was a necessity for the classical activation of astrocytes, which may aggravate injury in the acute phase of cerebral infarction." (PMID 31426811, 2019).
cyst (9 papers, 2015 to 2025). A sac-like closed membranous structure that may be empty or contain fluid or amorphous material. "LCN2, also known as neutrophil gelatinase-associated lipocalin (NGAL), is associated with cyst expansion in PKD in rodent models and humans." (PMID 41474822, 2025).
E. coli infection (9 papers, 2010 to 2025). "In a human cohort of women with recurrent E. coli UTIs, urine LCN2 levels were associated with UTI episodes and bacteriuria levels that were also related to the number of siderophore systems." (PMID 36555403, 2022). "It is known that the level of lipocalin 2 expression varies considerably between different individuals and it may thus be possible that this could play a role in the susceptibility to E. coli infections." (PMID 20633248, 2010). "In the urogenital tract, LCN2 is secreted by urethral mucosa and has been demonstrated to mitigate Escherichia coli infection in bladder epithelial cells by modulating JAK/STAT pathway activation, particularly under hyperglycemic conditions." (PMID 41196851, 2025). "Firstly, we showed that expression of lipocalin 2, a protein produced by the host that is able to both bind and deplete enterobactin, is increased upon E. coli infection in the cow's mastitic mammary gland." (PMID 33240956, 2020). "Pre-incubation with recombinant Lcn2 (rLcn2) restored LC3-II formation in DKO-derived TEPMs after E. coli infection, resulting in improved bacterial clearance in DKO-derived TEPMs." (PMID 27734904, 2016). "LCN2−/− mice have decreased survival following E. coli infection compared to wild-type mice." (PMID 24179676, 2013). "The protective effect against E. coli infection in wild type mice could be counteracted by the siderophore ferrichrome, indicating that the protective effect of lipocalin 2 depends on its ability to sequester iron." (PMID 20633248, 2010). "Mice that do not express lipocalin 2 have previously been demonstrated to be more susceptibility towards intraperitoneal E. coli infections than wild type mice." (PMID 20633248, 2010). "Therefore, we investigated the effect of Lcn2 deficiency on phagocytosis/autophagy pathways in macrophages by comparing LC3-II formation and p62 degradation between IL-10KO- and DKO-derived TEPMs after E. coli infection." (PMID 27734904, 2016). "The data presented here suggest that the lipocalin 2 released locally in the lungs either by import of myeloid cells or generated by the epithelial cells is an important factor in preventing dissemination of an E. coli infection in mice and suggests that this may also be the case in humans." (PMID 20633248, 2010).
experimental autoimmune encephalomyelitis (9 papers, 2017 to 2025). An autoimmune demyelinating disease of the central nervous system that is produced experimentally in animals by the injection of homogenized brain or spinal cord in Freund's adjuvant. "Three of those genes are upregulated in the Plus population: Slfn4 is known to be upregulated during macrophage activation, while Lcn2 and Slpi are both upregulated in the experimental autoimmune encephalomyelitis (EAE) model." (PMID 28720143, 2017). "Furthermore, experimental autoimmune encephalomyelitis (EAE) studies imply that LCN2 is a critical mediator of autoimmune inflammation and disease development in this model of MS." (PMID 35380252, 2022). "In addition to the protective role of stimulating the production of many antibacterial proteins (b-defensins, mucins: MUC5AC, MUC5B, S100 calgranulins, lipocalin 2), IL-17 appears to be important in autoimmunity as evidenced by the experimental autoimmune encephalomyelitis (EAE)." (PMID 31468124, 2019).
intestinal inflammation (9 papers, 2013 to 2023). "In a prior investigation of a gastroenteritis norovirus infection, elevated amounts of fecal LCN2 were discovered in Stat-deficient mice, demonstrating the relationship between LCN2 and GSDMD." (PMID 37240031, 2023). "Since fecal Lcn-2 is a sensitive biomarker for intestinal inflammation compared to other biomarkers, MS-associated intestinal inflammation and gut dysbiosis can be detected by the fecal Lcn-2 assay." (PMID 36341389, 2022). "After the AIEC-induced intestinal inflammation, fecal lipocalin-2 concentration was lower at day 6 in n-3 PUFAs supplementation groups (HFD-LS-O and HFD-LS-E) compared to HFD." (PMID 35682570, 2022).
nonalcoholic fatty liver disease (9 papers, 2020 to 2025). "On the contrary, hepatocyte-derived LCN2 protects against diet-induced nonalcoholic fatty liver disease by regulating lipolysis, fatty acid oxidation, de novo lipogenesis, and apoptosis or by interfering with expression of the lipid droplet associate protein Perlipin 5 (PLIN5)." (PMID 32718038, 2020). "For instance, in a non-alcoholic fatty liver disease (NAFLD) model study, it was found that Lcn-2 could trigger the secretion of HMGB1, activate TLR4 signaling pathway, induce NOX-2 expression, increase ROS production, then cause neuronal oxidative damage, which increase neuroinflammation." (PMID 38533497, 2024).
subarachnoid hemorrhage (9 papers, 2019 to 2025). A serious neurological disorder characterized by intracranial hemorrhage into the subarachnoid space. "In the study on the pathological mechanism of white matter damage caused by subarachnoid hemorrhage, LCN-2 was found to play an important role in the initiation and development of acute BBB disruption." (PMID 35493318, 2022). "However, in a different study, Egaschira reported that Lcn2 caused subarachnoid hemorrhage-induced blood-brain barrier disruption." (PMID 32622362, 2020). "Subarachnoid hemorrhage was induced in adult wild‐type or LCN2 knockout mice via endovascular perforation." (PMID 35150055, 2022). "LCN-2 deletion attenuates acute BBN leakage following subarachnoid hemorrhage." (PMID 35493318, 2022). "Subarachnoid hemorrhage causes very early BBB disruption and LCN2 expression in white matter that is associated with and may precede T2 hyperintensities." (PMID 31568658, 2019). "The current study examined whether white matter injury occurs in the hyperacute (4 hours) phase after subarachnoid hemorrhage (SAH) and the potential role of blood‐brain barrier (BBB) disruption and an acute phase protein, lipocalin 2 (LCN2), in that injury." (PMID 31568658, 2019).
tuberculosis (9 papers, 2012 to 2024). A chronic, recurrent infection caused by the bacterium Mycobacterium tuberculosis. "Lipocalin 2 has also been described as an important player in the tuberculosis granuloma formation." (PMID 37868350, 2023). "The function of lipocalin-2 in human tuberculosis is almost undescribed." (PMID 30534124, 2018). "Therefore, our findings in the mouse-model emphasize the importance of illuminating the role of lipocalin-2 in human tuberculosis." (PMID 30534124, 2018). "Lower neutrophil counts and lower circulating concentrations of neutrophil derived factors HNP1–3 and lipocalin 2 in these individuals when compared to people of South Asian and Caucasian origin, demonstrate the importance of neutrophils for the prevention of tuberculosis." (PMID 26803467, 2016). "Therefore, regulation of LCN2 production might represent an important therapeutic approach for future treatment of tuberculosis." (PMID 34563261, 2021). "In a recent study, serum levels of eotaxin, MIP-1α, sIL-2Rα, and lipocalin 2 were found different expressed in pulmonary tuberculosis patients vs. non TB patients." (PMID 29543810, 2018). "LTF and LCN2 were also induced during a septic shock, and MPO, LCN2, and LTF were used to distinguish between latent and active tuberculosis." (PMID 39409176, 2024). "Although the innate immune response is primarily important at the early stages of infection, previous in vivo tuberculosis studies have focused on the effect of lacking lipocalin-2 at later stages of infection, when the adaptive immune response dominates." (PMID 30534124, 2018).
abdominal aortic aneurysm (8 papers, 2014 to 2023). Enlargement and ballooning of the vessel that supplies arterial blood to the abdomen, pelvis and legs. "Genetic deletion of Lcn2 or injections of a NGAL neutralizing antibody protected against abdominal aortic aneurysm, with lower neutrophil infiltration and diminished MMP activity." (PMID 36510294, 2022).
Anorexia (8 papers, 2021 to 2024). Lack of desire to eat (loss of appetite). "Collectively, these studies support the notion that the pathologic upregulation of LCN2 contributes to the development of cancer-associated anorexia and both fat and lean mass wasting." (PMID 33824339, 2021). "A mouse model that investigated the effects of both deletion and rescue of Lcn2 found protection and sufficient induction of anorexia–cachexia syndrome, respectively." (PMID 38254849, 2024). "Given that anorexia in this model is reversible with melanocortin antagonists, this lends further support to the idea that normal homeostatic melanocortin signaling is bypassed by LCN2 acting as an MC4R agonist under pathological conditions." (PMID 35031523, 2022). "Lcn2 is derived in bone marrow and binds to melanocorticotropin 4 receptor (MC4R) in the hypothalamus, inducing anorexia." (PMID 38254849, 2024). "Although inflammation is sufficient to induce anorexia, the increased food intake during LCN2 blockade is independent of systemic inflammatory state and immunologic activation." (PMID 33824339, 2021).